Y_RNA (Y RNA )
Gene: Miscellaneous RNA gene on chromosome 2 (9,615,267 to 9,615,373, forward strand). Ensembl gene ENSG00000207086.
Homologues: Orthologues: chimpanzee Y_RNA (100% identical), guinea pig Y_RNA (89% identical), guinea pig Y_RNA (88% identical). Paralogues in human: RNY1P5 (88% identical), Y_RNA (87% identical), Y_RNA (86% identical), Y_RNA (84% identical), Y_RNA (82% identical), Y_RNA (81% identical), Y_RNA (80% identical), Y_RNA (79% identical), RNY1 (78% identical), Y_RNA (78% identical), RNY1P1 (77% identical), Y_RNA (77% identical), and 93 more.